GTF2I (general transcription factor IIi)
Diseases named in the same sentence as GTF2I in open-access papers (continued):
Sharing a sentence is not in itself a finding about the gene and the disease.
microcephaly (3 papers, 2012 to 2023). A congenital or acquired developmental disorder in which the circumference of the head is smaller than normal for the person's age and sex. "Heterozygotes of Gtf2i display microcephaly, retarded growth, and skeletal and craniofacial defects, indicative of the critical role of Tfii-i, the protein product of Gtf2i, dosage’s during embryonic development." (PMID 37626769, 2023). "It has been reported that GTF2I heterozygotes exhibit microcephaly and retarded growth." (PMID 33859276, 2021). "The majority of the literature discounts parent-of-origin effects in WBS, but there are reports of parent-of-origin effects on microcephaly and growth, as well as on GTF2I expression, both of which may be related to partial imprinting." (PMID 23118870, 2012). "GTF2I and GTF2IRD1 heterozygotes exhibit microcephaly and neural defects." (PMID 33859276, 2021).
systemic lupus erythematosus (3 papers, 2019 to 2022). An autoimmune multi-organ disease typically associated with vasculopathy and autoantibody production. "Genome-wide association studies of systemic lupus erythematosus (SLE) in Chinese and Korean populations demonstrated strong association of single nucleotide polymorphisms (SNPs) located in the GTF2I-NCF1 region, rs73366469 (GTF2I), rs117026326 (GTF2I), rs80346167(GTF2IRD1) and rs201802880 (NCF1)." (PMID 31705128, 2019).
autism (2 papers, 2014 to 2021). Persistent deficits in social interaction and communication and interaction as well as a markedly restricted repertoire of activity and interest as well as repetitive patterns of behavior. "Several candidate autism susceptibility genes were hypermethylated (P <0.05) in the HMFA, including Shank3, Cacana1g, Gtf2i, Rapgef4, and Nbea in male offspring and Ext1, Ube3a, Erbb4, Grip1, Grm8, Reeln, Shank3, and Rbfox1 in female offspring." (PMID 24484737, 2014).
diabetes (2 papers, 2011 to 2025). "Our objective was to determine the discriminatory performance of a molecular RNA panel comprising FZD5 and GTF2I for the early identification of ischemic heart disease in individuals with type 2 diabetes mellitus." (PMID 41244042, 2025). "this study identified clinically relevant non-coding RNA–based angiogenesis panel (FZD5, GTF2I mRNAs, hsa-miR-1976 and LINC02210 lncRNA) as a biomarker signature associated with type 2 diabetes mellitus complicated by ischemic heart disease." (PMID 41244042, 2025). "Therefore, we evaluated whether a molecular RNA panel comprising FZD5 and GTF2I could facilitate the early detection and discrimination of ischemic heart disease in individuals with type 2 diabetes mellitus." (PMID 41244042, 2025). "This aligns with our findings, which showed an elevated GTF2I mRNA in the T2DM+IHD group, suggesting its involvement in the development of IHD among patient with T2DM patients.MicroRNAs have emerged as informative biomarkers for diabetes and its sequelae." (PMID 41244042, 2025). "In our data, FZD5, GTF2I, hsa-miR-1976, and LINC02210 effectively differentiated T2DM from T2DM+IHD, consistent with prior reports identifying ncRNA signatures as candidate predictors of IHD in diabetes." (PMID 41244042, 2025).
viral infection (2 papers, 2023 to 2025). "To evaluate the successful deletion of Gtf2i in infected cells at single-cell resolution, we performed immunostaining for mCherry (indicating virus infection) and Tfii-i." (PMID 37626769, 2023). "All cells that were infected with the Cre-positive virus showed no expression of Tfii-i, indicating efficient knockout of Gtf2i following viral infection." (PMID 37626769, 2023).
acute coronary syndrome (1 paper, 2025). Signs and symptoms related to acute ischemia of the myocardium secondary to coronary artery disease. "has-miR-1976 was found to interact with the selected genes, FZD5 and GTF2I and was strongly linked to acute coronary syndrome and diabetic nephropathy progression." (PMID 41244042, 2025).
anxiety disorder (1 paper, 2021). A category of psychiatric disorders which are characterized by anxious feelings or fear often accompanied by physical symptoms associated with anxiety. "Phenotype genotype correlation is poor, except for involvement of elastin and Gtf2i genes showing increased risk of aortic dilatation and anxiety disorder, respectively." (PMID 33269527, 2021).
Arthritis (1 paper, 2016). Inflammation of a joint. "These congenic strains conclusively identified a minimal arthritis-protective interval of 300 kb that contained only two genes, Ncf1 and Gtf2i (general transcription factor IIi)." (PMID 27736747, 2016).
atrial fibrillation (1 paper, 2025). A disorder characterized by an electrocardiographic finding of a supraventricular arrhythmia characterized by the replacement of consistent P waves by rapid oscillations or fibrillatory waves that vary in size, shape and timing and are accompanied by an irregular ventricular response. "However, there are exceptions to this trend such as is observed in atrial fibrillation, where GATA4, GTF2I, and CASZ1 are both CVD proteins and DOX-correlated hub proteins." (PMID 40469117, 2025).
B cell lymphoma (1 paper, 2025). "GTF2I is tumorigenic, enhancing cell proliferation of B cell lymphoma and lymphoblastic leukemia." (PMID 40007754, 2025).
bipolar disorder (1 paper, 2017). A disorder of the brain that causes unusual shifts in mood, energy, activity levels and the ability to carry out day-to-day tasks. "This gene list includes new excellent candidates with putative links to bipolar disorder, including ADK, GTF2I, hnRNP-A1, HTRA2, PKD1 and RERE, which have been linked to various brain-related diseases." (PMID 28915787, 2017).
brain tumor (1 paper, 2017). "In the present study we report for the first time a GTF2I-BRAF fusion in a pediatric brain tumor." (PMID 28448514, 2017).
breast adenocarcinoma (1 paper, 2025). "Although H3F3A, CARS, GTF2I and SEPT9 are not IntOGen genes of the three cohorts (colored by yellow), they have been proved to play important roles in the development of breast adenocarcinoma." (PMID 40768543, 2025).
cervical cancer (1 paper, 2021). A primary or metastatic malignant neoplasm involving the cervix. "Moreover, IPO7 contributed to activating the PI3K/AKT-mTOR pathway by mediating the nuclear import of GTF2I in cervical cancer cells." (PMID 34650978, 2021).
Coagulopathy (1 paper, 2022). "Coagulopathy was reported in GTF2I-RARA, FNDC3B-RARA, NUP98-RARA, and TNRC18-RARA-positive AML." (PMID 35494081, 2022).
cognitive delay (1 paper, 2014). "LIMK1, GTF2I and GTF2IRD1 genes have been related to aspects of cognitive delay." (PMID 25016475, 2014).
ischemic heart disease (1 paper, 2025). "Independent reports indicate that increased methylation of GTF2I is associated with a higher subsequent risk of myocardial infarction and coronary heart disease." (PMID 41244042, 2025).
lentivirus infection (1 paper, 2019). Virus diseases caused by the Lentivirus genus. "In order to investigate the mechanism and resistant phenotype of GTF2I-RARA, we established a GTF2I-RARA stably expressed cell line by lentivirus infection." (PMID 30992691, 2019).
lupus nephritis (1 paper, 2020). Glomerulonephritis in the context of systemic lupus erythematosus. "Interestingly, the variants on STAT4 and GTF2I loci were correlated with lupus nephritis (LN) in the various SLE ancestries." (PMID 32771030, 2020).
melanoma (1 paper, 2017). A malignant, usually aggressive tumor composed of atypical, neoplastic melanocytes. "Interestingly, another GTF2I-BRAF fusion (exon 4–10) has been reported in one primary melanoma case, supporting a role of this fusion partnership in tumor development." (PMID 28448514, 2017).
myopia (1 paper, 2022). "On the one hand, the results of Metascape revealed a potential role of TF in the development of myopia with the enrichment of Smad6, NrOb2, Gtf2i, Tfap2a, Pax7, Pax6, Sox9 and Smad3." (PMID 34841657, 2022).
osteoporosis (1 paper, 2025). A condition of reduced bone mass, with decreased cortical thickness and a decrease in the number and size of the trabeculae of cancellous bone (but normal chemical composition), resulting in increased fracture incidence. "Our study also verified that GTF2I affected osteoporosis in mice through the miR‐134‐5p/MAT2A axis." (PMID 40191097, 2025).
cancer (28 papers, 2011 to 2025). A tumor composed of atypical neoplastic, often pleomorphic cells that invade other tissues. "Non-recurrent, cancer-specific mutations (n = 28 genes across 11 cancers) predominantly correlated with high telomerase activity, with notable exceptions including PPP2R1A in UCS, HRAS, and GTF2I in THYM and SMAD4 in PAAD." (PMID 41321994, 2025). "GTF2I has been recently named gene of the month and its role in cancer reviewed (Nathany, Tripathi & Mehta, 2021)." (PMID 35975235, 2022). "Novel studies have shown that GTF2I is involved in an array of human diseases including neurocognitive disorders and cancer." (PMID 34248934, 2021). "Seven cofactors (TFAP2A, E2F, GSTM1, IL6, PATZ1, MEF2A and GTF2I) identified in two of the five cancer types have general functions in cancers." (PMID 28684851, 2017). "By the most comprehensive measure (Transcriptomic Distance, TD), POLR2L had the largest contribution to the overall cancer-induced transcriptomic alteration within this gene subset in T (TD(T) = 145, TD(Φ) = 497, TD(Θ) = 495) and GTF2I in both cell lines (TD(T) = 45, TD(Φ) = 964 TD(Θ) = 872)." (PMID 38790250, 2024). "We identified several TFs, including GTF2I, NFIB, NFATC4, ZNF37A, KLF13, and ZNF507, involved in cancer metastasis." (PMID 39273015, 2024). "Using knockdown approaches of GTF2-I or BCLAF-1 we showed that these two transcription factor do not participate to the regulation of cancer cells migration." (PMID 31527668, 2020). "However, recent studies showed that different BRAF fusions, such as GTF2I-BRAF, DGKI-BRAF, and TMEM106B-BRAF, activated the MAPK pathway, thereby regulating tumor growth in multiple cancers." (PMID 30111351, 2018). "However, some genes such as General Transcription Factor IIi (GTF2I) are not (yet) registered as known tumor suppressor genes and oncogenes in the COSMIC cancer gene census database." (PMID 39230704, 2024).
tumor (23 papers, 2011 to 2025). "The most common mutation observed is the missense L424H mutation in GTF2I, which is unique to this type of neoplasm." (PMID 37671056, 2023). "The staining intensity of PD-L1 was significantly higher in the GTF2I+ group compared to in the GTF2I− group, which suggests the mutually exclusive presence of PD-L1 expression and the GTF2I mutation in tumor cells." (PMID 32722121, 2020). "Moreover, in the present evaluation, tumor specimens were sampled from the resected mass and immediately frozen, potentially increasing the detection rate of GTF2I mutations using highly sensitive technologies." (PMID 37671056, 2023). "In addition, the clinicopathologic characteristics such as age, gender, GTF2I mutation, histologic subtype, MG history and Masaoka stage also demonstrated that patients in the low-risk group had lower odds of tumor recurrence compared with the high-risk group." (PMID 36114454, 2022). "The human tumor samples that metabolically resemble fly tumors showed strong enrichment for mutations in IDH1, GTF2I and ATRX." (PMID 40523311, 2025). "Survival curves showed that patients in the GTF2I mutant-type group had more favorable prognostic results with lower probabilities of tumor recurrence than the GTF2I wild-type group." (PMID 36114454, 2022). "We determined that three oncogenes, PD-L2, ETV5, and MTOR and 113 long intergenic non-coding RNAs (lincRNAs) were constantly up-regulated, whereas two oncogenes, BCR and GTF2I, one tumor suppression gene MEN1, and 30 lincRNAs were constantly down-regulated." (PMID 35317849, 2022). "GTF2I L424H knockin cells exhibit cell transformation, aneuploidy, and increased tumour growth and survival under glucose deprivation or DNA damage." (PMID 35975235, 2022). "However, limited research has been conducted on the role of GTF2I in the tumor immune microenvironment (TIME)." (PMID 36114454, 2022). "Therefore, this study aimed to explore the relationship between GTF2I mutations and TIME and build a new potential signature for predicting tumor recurrence in the TETs." (PMID 36114454, 2022). "Using a LEfSe analysis, we identified variations in specific species between type A and B tumors and between tumors with and without the GTF2I mutation, indicating the differential microbiome functions in the development of each type of tumor." (PMID 34834444, 2021). "In the present study, we found that IPO7 activates PI3K/AKT-mTOR pathway to exert oncogenic function in CC cells by transporting GTF2I into the nucleus, which could provide clear information for the future of tumor treatment research." (PMID 34650978, 2021). "PyClone analysis revealed a high cellular prevalence of mutant GTF2I in tumor cells." (PMID 32722121, 2020).
neurodevelopmental disorder (8 papers, 2012 to 2024). A behavioral and cognitive disorder with onset during the developmental period that involves impaired or aberrant development of intellectual, motor, or social functions. "Although no in vivo neuronal targets of GTF2IRD1 were detected, possible GTF2I targets included genes involved in axon guidance, neurodevelopmental disorders, calcium signaling, cell cycle, and immune response." (PMID 23118870, 2012). "Moreover, we validated mitochondrial and autophagy-related deficits in human brain samples derived from individuals with WS, a neurodevelopmental disorder involved with GTF2I haploinsufficiency." (PMID 38097729, 2023). "Moreover, the rationale for exploring the impact of post-natal Gtf2i deletion lies in the potential for developing therapeutic interventions for neurodevelopmental disorders and other pathological conditions beyond current behavioral therapies and pharmaceutical agents." (PMID 37626769, 2023).
infection (6 papers, 2015 to 2025). The state of being infected such as from the introduction of a foreign agent such as serum, vaccine, antigenic substance or organism. "This targeted deletion was performed in young mice, allowing for precise and efficient brain-wide infection leading to the exclusive removal of Gtf2i from excitatory neurons." (PMID 37626769, 2023).
GTF2I also shares sentences with these, for which no sentence is quoted: genetic disorder (4 papers); pulmonary fibrosis (4); pulmonary hypertension (3); autoimmune disorders (2); Cognitive impairment (2); hepatocellular carcinoma (2); lung diseases (2); ovarian carcinoma (2); rheumatoid arthritis (2); thymic tumor (2); ANCA-associated vasculitis (1); Andersen syndrome (1); arrhythmogenic right ventricular cardiomyopathy (1); asthma (1); basal cell carcinoma (1); brain cancer (1); bronchopulmonary dysplasia (1); Burkitt lymphoma (1); chronic obstructive pulmonary disease (1); Cockayne syndrome-B (1); colorectal cancer (1); diabetic nephropathy (1); dilated cardiomyopathy (1); dyslexia (1); epilepsy (1); erythroleukemia (1); gastric cancer (1); H1N1 influenza A (1); HIV-1 infection (1); Hypercalcemia (1).
A further 24 diseases each share a sentence with GTF2I in 1 paper.